ATM (ATM serine/threonine kinase)
Diseases named in the same sentence as ATM in open-access papers (continued):
Sharing a sentence is not in itself a finding about the gene and the disease.
cancer (continued). "Inhibition of ATM reduced both glycolytic enzymes and OXPHOS levels in oncogene-driven cancer cells and enhanced apoptosis induced by driver inhibitors thus highlighting the possibility to use ATM and the driver inhibitors in combined regimens of anticancer therapy in vivo." (PMID 37932830, 2023). "In addition, the expression and secretion of IFNβ was elevated in response to ATM inhibition in various cancer cell lines (H157, A549, MC-38, CT26, and B16-F10)." (PMID 36778120, 2023). "Here, we dive deeper into the cellular events in irradiated cancer cells exposed to ATM inhibitors." (PMID 36656721, 2023). "It is presently unknown whether ATM has a specific role in the acquisition or maintenance of the glycolytic phenotype in cancer cells and more importantly whether there are intersections between the oncogene-driven mitogenic pathways and ATM signaling." (PMID 37932830, 2023). "Undoubtedly, ATM mutations cause genomic instability and defects in DDR and cell-cycle checkpoint control, which promote resistance to apoptosis and occurrence and development of cancer." (PMID 37674118, 2023). "This gives additional drug-repurposing insight, that the drug KU-60019, originally developed as a drug targeting ATM, could be used to target cancers with PRKDC LoF alteration." (PMID 37120674, 2023). "The aim of the present study is to elucidate the role of ATM in the regulation of glucose metabolism in cancer cells and to test whether ATM is a suitable target for anticancer therapy." (PMID 37932830, 2023). "The aim of our study is to elucidate the role of ATM in the regulation of glucose metabolism in oncogene-driven cancer cells and to test whether ATM may be a suitable target for anticancer therapy." (PMID 37932830, 2023). "Collectively, these results suggest an influence of ATM on the cancer cell killing of VP-16." (PMID 36650267, 2023). "Moreover, as ATM inhibitors have already been extensively evaluated in clinical trials, our work underscores Gal-9-targeted cancer immunotherapy as a promising modality that can be evaluated in future clinical trials in combination with these ATM inhibitors." (PMID 36778120, 2023). "Two variants in ATM and BRCA1 were identified in patients with a family history of cancer." (PMID 37234870, 2023). "Among the younger group, 53 had BRCA1/2 germline PVs/LPVs (38%), 15 were carriers of other cancer susceptibility genes (10%), primarily APC, NBN, ATM, MUTYH, MLH1, and only 2 patients were carriers of PVs/LPVs in both BRCA1/2 and other susceptibility genes (1%)." (PMID 38136276, 2023). "Furthermore, our research has shown underexpression of genes associated with tumor formation and cancer cell migration, including AKT Serine/Threonine Kinase 3 (AKT3), Serine/Threonine Kinase (ATM) and Pseudopodium Enriched Atypical Kinase 1 (PEAK1) gene." (PMID 38074096, 2023). "For instance, ATM expression can be decreased in some cancers due to miRNA-18a." (PMID 37081847, 2023). "In ACP52C‐treated cancer cells, we also observed an increase in DNA strand breaks (SBs) and an upregulation of DNA damage responses (DDRs) markers, including γH2AX, as well as phosphorylated ATM, ATR, CHK1, and CHK2." (PMID 37845006, 2023). "Numerous ATM inhibitors are currently being researched for cancer treatment." (PMID 36902170, 2023). "Given the important role of IFNβ in upregulating Gal-9 expression 8, we thus evaluated whether STING-IFNβ pathway is activated in response to ATM inhibition in these cancer cell lines." (PMID 36778120, 2023). "Moreover, we found that THZ531 synergically enhanced the cytotoxic activity of targeted DNA damage-inducing agents, such as Olaparib, ATR and ATM inhibitors, that are in use or being evaluated in clinical trials for other cancer types." (PMID 37599362, 2023).
cancer (continued). "Therefore, it was suggested that the reduced expression of ATM and its phosphates is significantly involved in cancer malignancy and gemcitabine resistance." (PMID 37674118, 2023). "ATM inhibition can also enhance radiation-induced inflammatory signaling and cancer cell death." (PMID 37174688, 2023). "To evaluate for genotype-phenotype correlations, we compared the pathogenic ATM variants in the 6 atypical cancer cases to the 25 typical cancer cases, though no clear differences were evident." (PMID 36865800, 2023). "Therefore, it is clinically important to characterize pathogenic ATM/ATR mutations, which would in turn help infer the involvement of other variants of uncertain significance of these two PIKK genes in cancer." (PMID 38041093, 2023). "If there was a clinical trial indication at level C or D for a specific cancer type, such as amplification of MDM2 or FGFR1 or mutations of AKT1, ATM, CDK12, and PTEN, patients were considered as candidates for receiving treatment, although in most cases, no clinical trials were available." (PMID 36251535, 2023). "ATM-rs228590 may, therefore, upregulate the function of the pathway, thus resulting in increased cancer cell proliferation, increasing the development of BC." (PMID 36152082, 2023). "Furthermore, one aspect should be taken into account in the future, since previously published data postulated an elevated level of ATM expression in several cancer cells." (PMID 36229655, 2023). "Thus, ATM-targeting drugs hold promise in treating cancers, and one such drug has reached clinical trials." (PMID 36765693, 2023). "This study was conducted on cancer-associated fibroblasts (CAF) and the human breast cancer cell line MDA-MB-231, as well as on nude mice, to unveil the role of oxidised ataxia-telangiectasia (ATM) in the regulation of glycolysis during hypoxia." (PMID 36761981, 2023). "Both DNA-PK and ATM inhibitors prolong the life of radiation induced DSBs and could serve as potent enhancers of inflammatory signaling and cancer cell death, offering potential new agents for combination radiotherapy." (PMID 36656721, 2023). "However, it is noted that the regulation of ATM in BCSCs can be complex and have opposing effects on the response to cancer therapy." (PMID 37958993, 2023). "Consequently, there is a need of a delivery system for ATM inhibitors that, ideally, specifically targets cancer stem cells." (PMID 36900267, 2023). "To date, various ATM inhibitors have been investigated for cancer treatment." (PMID 37958890, 2023). "A case-control analysis for each of the atypical-ATM cancer types could have also provided compelling evidence of an association." (PMID 36865800, 2023). "ATM is also involved in oxidative stress (redox) control, mitochondria, and autophagy in cancer." (PMID 37511215, 2023). "Following large‐scale cancer sequence analysis, mutations in other HR‐related genes such as CDK12, ATM and PALB2 were commonly found in mCRPC, and these non‐BRCA DNA repair genes could be used as alternative biomarkers to predict the sensitivity of PARPi." (PMID 36694344, 2023). "Epigenetic defects of the ATM gene have been observed at a high rate in a variety of cancer cells." (PMID 37514113, 2023). "In the combined treatment, inhibition of ATM may have reduced the cellular response to DSBs and thereby induced DSBs in a larger number of cancer cells." (PMID 36765693, 2023). "In conclusion, we showed that cancer cells expressing high levels of RYBP have lower ATM activity." (PMID 36233063, 2022). "ATM is the causing gene of ataxia-telangiectasia (AT) (OMIM #208900), which is an autosomal recessive inherited disease, and it is associated with recurrent upper and lower respiratory tract infections and a trend for increased susceptibility to cancers." (PMID 34825286, 2022).
cancer (continued). "Furthermore, they found that silencing ATM abolishes autophagy and apoptosis while promoting cancer development whereas, overexpression of ATM suppresses proliferation." (PMID 35318393, 2022). "Although the functions of ATM signaling in cancer cells have been widely studied, the impact of ATM and its inhibition on other aspects of cancer cells remain unclear." (PMID 35795059, 2022). "Ataxia telangiectasia mutated (ATM) is a key mediator of the DNA damage response with a crucial role in maintaining genomic integrity, making it significant in the study and therapy of cancer." (PMID 35962885, 2022). "Taken together, our results suggest that ATM inhibition may promote SKOV3 cell apoptosis via suppressing hsa-miR-542-5p and elevating OGT and OGA expression, providing new insights into the application of ATM inhibitors in cancer immunotherapy." (PMID 35795059, 2022). "Contrary to RYBP, inhibiting ATM activity in cancer cells sensitizes them to DNA damage." (PMID 36233063, 2022). "Aberrations in the ATM gene are commonly observed in cancer." (PMID 35008949, 2022). "Over-activation of ATM promotes the adaptation of cancer cells to genotoxic stress." (PMID 35897717, 2022). "ATM has become a promising target to develop sensitizers for cancer radiotherapy and chemotherapy." (PMID 35372071, 2022). "Furthermore, ATM can promote cancer cell migration by regulating the expression of IL-8 independent of its role in the repair of DNA double-strand breaks." (PMID 36071479, 2022). "Interestingly, a previous study showed that ATM activation persists in cancer cells and mediates selective killing effects of the viral protein, apoptin." (PMID 36233063, 2022). "There were no abnormal cancer related findings after screening in the two patients with the FH and ATM variants." (PMID 35719373, 2022). "The ABL1-I418T, PIK3CB-R231H, CHEK2:c.-4C > T, BRCA2-P3292L, ABL1-E459G, PRPF8-G1796R, PHF6-R274Q, WT1-R435X and ATM-C117Y variants were potentially important cancer variants which were not actionable." (PMID 35896598, 2022). "Aberrations in the ATM gene are also commonly observed in cancer, some of which may be of germline origin." (PMID 35008949, 2022). "ATM in cancer cells tend to be upregulated more often than downregulated." (PMID 36233063, 2022). "However, when the ERBB2 expression in cancer is impaired compared with the matching normal tissue, the ATM level increases compared with the matching normal tissue, as illustrated in colon, kidney renal clear cell and kidney renal papillary cell cancers." (PMID 36056635, 2022). "ATM inhibition by RYBP may further provide a new mechanism by which RYBP sensitizes cancer cells to DNA damage and PARP inhibitors." (PMID 36233063, 2022). "Additionally, the ATM serine/threonine kinase was found as a hub and is involved in focal adhesion and actin cytoskeleton rearrangement in cancer progression." (PMID 35323480, 2022). "Interestingly, we noticed that when the ERBB2 level is high in cancer compared with the matching normal tissue, the ATM level in cancer shows deregulation compared with ATM levels in normal matched tissue." (PMID 36056635, 2022). "However, the hypervariability due to the large size of this gene, and the fact that several of the identified variants are variants of uncertain significance (VUSs), pose a challenge to the inclusion of additional tumors in the ATM-related cancer spectrum." (PMID 36555667, 2022).
cancer (continued). "The study presents the ATM/autophagy axis as a key player for cell fate between senescence and apoptosis, therefore suggesting that autophagy can be a target to induce G4 ligand-dependent cancer cell death." (PMID 36114513, 2022). "Because of their non-redundant and coupled functions, ATR and ATM kinases were for a long time seen as putative co-targets for drug combination in cancer therapy." (PMID 35361811, 2022). "Published data demonstrated that targeting the ATM may impact treatment efficacy and improve the outcome of cancer patients." (PMID 36056635, 2022). "AT heterozygous (individuals with a single pathogenic ATM variant) have none of the classic clinical manifestations of AT, but have increased cancer risk." (PMID 35163129, 2022). "No hereditary cancer predisposition linked to the germline mutations K1992T, G2023R, and L2492R in ATM as well as R466C, R5229H, and S5357T in KMT2D were observed." (PMID 35347810, 2022). "Having established that ATM inhibition can be used to effectively target cancer cells that survive EGFR inhibitor therapy, we sought to evaluate whether these findings could be extended to other DDR pathway inhibitors through a similar mechanism." (PMID 35353542, 2022). "In addition, classic cancer driver genes identified in other cancers were also identified as SMGs in this study, including ATM (3.45%, 12/348), BRCA2 (2.01%, 7/348), and MLLT4 (2.01%, 7/348)." (PMID 35650238, 2022). "Increased expression of TRF2 in response to short telomeres is a factor of poor prognosis, because ATM-dependent apoptosis may be more strongly inhibited, and this allows the cell to survive and cancer to progress." (PMID 36612286, 2022). "By analyzing hundreds of fibroblast cell lines derived from cancer patients eliciting a large spectrum of post-radiotherapy radiosensitivity, it appears that IR triggers a drastic change in the subcellular localization of ATM." (PMID 36551628, 2022). "No additional variants in the ATM gene or other variants associated with cancer predisposition were identified by either genetic test." (PMID 36414972, 2022). "Among those, the main function of AKT, ERK1/2, and NF-κB signalings is to block apoptosis induction in the irradiated cancer cells, while the primary functions of the ATM, ATR, and DNA-PK signalings are to promote the cell cycle checkpoint activation and DNA repair in cancer cells." (PMID 35328212, 2022). "There is an urgent and currently unmet need to provide robust information that can inform risk management strategies for carriers of pathogenic variants in intermediate risk genes such as ATM and CHEK2, as these genes are now routinely included on gene panels for cancer predisposition." (PMID 35365198, 2022). "According to the local testing criteria in use, 73.2% of patients included in this study underwent genetic testing, and 30% of them presented germline likely pathogenic or pathogenic variants in cancer predisposition genes (24 BRCA1, 4 BRCA2, 1 PALB2, 1 NBN, and 1 ATM)." (PMID 36531080, 2022).
cancer (continued). "Indeed, following the success of PARP inhibitors, ATM inhibitors have been proposed in the therapeutic exploitation of DNA Damage Response (DDR) in cancer." (PMID 35794609, 2022). "Additionally, MSI cancers showed a significant downregulation of both ATM checkpoint signaling and mast cell abundance, which is a signature measuring macrophages in the tumor microenvironment." (PMID 36010943, 2022). "The present evidence suggests that ATM germline mutations are not cancer type-specific, because they have been reported in many cancers and have been suggested to potentially increase the risk of some cancers." (PMID 35014770, 2022). "Altogether, this data indicates that targeting patients carrying both HER2 and ATM mutations using anti‐ATM and anti‐HER2 combination therapy may provide extra benefit for cancer patients." (PMID 36056635, 2022). "Recent findings suggest that ATM inhibition reduces cancer cell migration." (PMID 36233063, 2022). "In addition, the acquisition of the fibroblastic shape in cells derived from carcinomas seems to require inflammation, the DNA damage response, and the activity of ATM, NF-κB, and the EMT transcription factors." (PMID 35806442, 2022). "They attenuate ATM activation and HR repair, sensitizing genotoxic treatment in cancers." (PMID 34359720, 2021). "The dual dNTP pool targeting of emodin (increasing ROS on one hand and inhibiting oxidized dNTP pool sanitation by MTH1 on other) shows an additive effect on apoptotic cancer cell death, highlighted by augmented DNA damage and corresponding ATM repair pathway upregulation." (PMID 33403025, 2021). "Additionally, the nuclear ATM/ATR/CHK1 kinase signaling pathway can modulate PD-L1 expression following DNA damage by phosphorylating STAT1/3 (in the cytoplasm) in cancer cells." (PMID 34930377, 2021). "Using a multivariate regression model, corrected for age and genetic ancestry represented by principal components, we found 12 positive correlations between the HRD score and germline variants in five (i.e., BRCA1, BRCA2, PABL2, ATM, ATR) genes across cancer types." (PMID 34572800, 2021). "Promoting ATM signaling and expression may facilitate cancer cells’ resistance to chemotherapy and radiation, metastasis, and tumor cell survival." (PMID 34070860, 2021). "As regards therapeutic implications, ATM aberrations may sensitize cancer cells to platinum-derived drugs, similarly to the effect of BRCA1 mutations, but have a worse effect in case of radiotherapy (RT)." (PMID 34068084, 2021). "Therefore, besides a PARP inhibitor, an ATM-specific inhibitor would be another attractive therapeutic approach for eliminating cisplatin-refractory cancer cells if combined with cisplatin." (PMID 34948122, 2021). "While, ATR loss of function is rare in cancers, ATR inhibition may be particularly potent in cancer cells with other, specific mutations, such as in ATM, when compared to normal cells." (PMID 33498525, 2021). "Importantly, a link was established between ARF and the DNA double-strand break sensor Ataxia Telangiectasia Mutated (ATM), demonstrating that, following genotoxic stress in cancer cells, ATM negatively regulates ARF protein levels." (PMID 33445626, 2021). "Though there were no other GWAs in HNC to be compared, the ATM associated pathway in two cancers seems interestingly linked to the functional analysis of annotation of the 16 GWSdiscovery SNPs." (PMID 34838041, 2021). "However, the results showed that combining of ATM and DNA-PK inhibitors with α-radiation in cancer cell as well as normal HEK293 cell line sensitized to a lower degree as compared to combination with X-rays." (PMID 34853427, 2021). "Here, we hypothesized that IR-induced ataxia telangiectasia mutated (ATM) activation following direct interaction with DCLK1 may lead to the repair of damaged DNA, and increase the survival of cancer cells." (PMID 34268251, 2021).